TUBA3E (tubulin alpha 3e)
Description:
Tubulin is the major constituent of microtubules, a cylinder consisting of laterally associated linear protofilaments composed of alpha- and beta-tubulin heterodimers. Microtubules grow by the addition of GTP-tubulin dimers to the microtubule end, where a stabilizing cap forms. Below the cap, tubulin dimers are in GDP-bound state, owing to GTPase activity of alpha-tubulin.
Tractability: Small molecule: an approved drug acts on it; a high-quality ligand is known; it belongs to a druggable protein family. PROTAC: ubiquitination databases record sites on it; a small molecule that binds it is known. Other modalities: an approved drug acts on it.
Gene: Protein-coding gene on chromosome 2 (130,191,745 to 130,198,439, reverse strand). Ensembl gene ENSG00000152086.
Subcellular location: Cytoplasm, cytoskeleton
Subcellular location (Human Protein Atlas): Microtubules; Primary cilium
Pathways (Reactome):
Cell Cycle: EML4 and NUDC in mitotic spindle formation; Mitotic Prometaphase; Recruitment of NuMA to mitotic centrosomes; Resolution of Sister Chromatid Cohesion; Sealing of the nuclear envelope (NE) by ESCRT-III; Separation of Sister Chromatids; The role of GTSE1 in G2/M progression after G2 checkpoint
Vesicle-mediated transport: COPI-dependent Golgi-to-ER retrograde traffic; COPI-independent Golgi-to-ER retrograde traffic; COPI-mediated anterograde transport; Gap junction assembly; Microtubule-dependent trafficking of connexons from Golgi to the plasma membrane; Translocation of SLC2A4 (GLUT4) to the plasma membrane
Metabolism of proteins: Carboxyterminal post-translational modifications of tubulin; Formation of tubulin folding intermediates by CCT/TriC; Post-chaperonin tubulin folding pathway
Immune System: MHC class II antigen presentation; PKR-mediated signaling
Neuronal System: Activation of AMPK downstream of NMDARs; Assembly and cell surface presentation of NMDA receptors
Signal Transduction: RHO GTPases Activate Formins; RHO GTPases activate IQGAPs
Autophagy: Aggrephagy
Cellular responses to stimuli: HSP90 chaperone cycle for steroid hormone receptors (SHR) in the presence of ligand
Developmental Biology: Recycling pathway of L1
Disease: HCMV Early Events
Hemostasis: Kinesins
Organelle biogenesis and maintenance: Cargo trafficking to the periciliary membrane
Gene Ontology:
Molecular function: protein binding; GTP binding; GTPase activity; structural constituent of cytoskeleton
Biological process: mitotic cell cycle; cytoskeleton organization; microtubule-based process
Cellular component: microtubule cytoskeleton; nucleus; cytoskeleton; microtubule
Genetic constraint (gnomAD): Loss-of-function variants: 21 observed, 34.37 expected, observed/expected ratio (o/e) 0.61, 90% interval 0.43 to 0.88. The synonymous counts are far from expectation, so gnomAD's model fits this gene poorly and the ratio says little. Missense variants: 469 observed, 579.04 expected, observed/expected ratio (o/e) 0.81, 90% interval 0.75 to 0.87. Synonymous variants: 177 observed, 228.36 expected, observed/expected ratio (o/e) 0.78, 90% interval 0.69 to 0.88.
Homologues: Orthologues: chimpanzee TUBA3C (99% identical), rat Tuba3a (99% identical), macaque TUBA3E (98% identical), Drosophila melanogaster alphaTub84B (96% identical), Drosophila melanogaster alphaTub84D (96% identical), zebrafish tuba7l (93% identical), tropical clawed frog tuba1cl (63% identical). Paralogues in human: TUBA3C (99% identical), TUBA3D (99% identical), TUBA1A (96% identical), TUBA1B (96% identical), TUBA1C (95% identical), TUBA4A (93% identical), TUBA8 (90% identical), TUBAL3 (72% identical), TUBB4B (42% identical), TUBB4A (42% identical), TUBB (41% identical), TUBB3 (41% identical), and 11 more.
Diseases named in the same sentence as TUBA3E in open-access papers:
TUBA3E is named in the same sentence as 6 diseases in open-access papers, as found by Europe PMC text mining. Sharing a sentence is not in itself a finding about the gene and the disease. The quoted sentences say what the papers report.
breast carcinoma (1 paper, 2017). "Top HBF + BPA-dysregulated genes (ALDH1B1, ASTL, CA7, CPLX4, KCNV2, MAGEE2 and TUBA3E) are associated with poor overall survival in The Cancer Genomic Atlas (TCGA) human breast cancer cohort (n = 1082)." (PMID 28487351, 2017). "We took advantage of the publicly available RNA-seq and survival data from TCGA and determined that seven differentially expressed genes (ALDH1B1, ASTL, CA7, CPLX4, KCNV2, MAGEE2 and TUBA3E) could be involved in breast cancer development, especially in Caucasian female patients with ER positivity." (PMID 28487351, 2017). "To gain clinical significance, using The Cancer Genomic Atlas (TCGA) breast cancer cohort, we dichotomized 1082 breast cancer subjects into two groups based on the expression of the seven genes (ALDH1B1, ASTL, CA7, CPLX4, KCNV2, MAGEE2 and TUBA3E)." (PMID 28487351, 2017). "Interestingly, expression of four genes (ALDH1B1, ASTL, CA7 and TUBA3E) of the seven gene panel was significantly different between the two groups of human breast cancer subjects (data not shown)." (PMID 28487351, 2017).
breast invasive lobular carcinoma (1 paper, 2024). "Specifically, TUBA3D and TUBA3E showed abnormally high expression in breast invasive lobular carcinoma cell lines, whereas the other 3 genes displayed either low or high expression in varying contexts." (PMID 39432642, 2024).
dilated cardiomyopathy (1 paper, 2025). Cardiomyopathy which is characterized by dilation and contractile dysfunction of the left and right ventricles. "Downregulation of TUBA3D and TUBA3E has been identified in dilated cardiomyopathy (DCM,) and may be a significant molecular alteration contributing to the disease." (PMID 41304893, 2025).
TUBA3E also shares sentences with these, for which no sentence is quoted: cardiomyopathy (1 paper); infection (1); polyp (1).